CCL2 (C-C motif chemokine ligand 2)
Diseases named in the same sentence as CCL2 in open-access papers (continued):
Sharing a sentence is not in itself a finding about the gene and the disease.
tumor (continued). "These revealed that in patients with LUAD (a tumor with high KRAS mutation frequency), high KRAS/CCL2/IL1B expression levels portended 93% increased odds of death regardless of smoking status (upper left)." (PMID 35327394, 2022). "M2-like TAMs secrete a variety of chemokines and interleukins including CCL2, IL-6 and IL-10, to enhance tumor cell proliferation." (PMID 35672862, 2022). "Both cytokines can modify the tumor microenvironment, either by directly influencing angiogenesis or via recruiting macrophages (CCL2) and activating fibroblasts (OPN)." (PMID 36230508, 2022). "Adipocytes and BC tumor cells release chemokines (e.g., C-C motif chemokine ligand 2 (CCL2), C-C motif chemokine ligand 5 (CCL-5), or colony-stimulating factor (CSF-1)) to promote the migration of monocytes and macrophages into the BC microenvironment." (PMID 36364213, 2022). "Meanwhile, studies reported tumor and stromal cells in the tumor microenvironment release chemokines (for instance, CCL2 and CCL5) and cytokines (such as CSF-1 and VEGF), recruiting circulating monocytes, resulting in tumor-associated macrophages (TAMs)." (PMID 36421355, 2022). "Similar results were observed in A549 tumours, but in this model, C‐1305 enhanced the plasma level of CCL2 significantly." (PMID 35701366, 2022). "The IHC grade of CCL2 in HER2-positive GC tissues was significantly increased compared with that in HER2-negative tumor tissues." (PMID 35851310, 2022). "Later research established a reciprocal relationship between endocrine-resistant breast tumor cells and TAM linking endocrine resistance in tumor cells to CCL2 secretion promoted by TAM." (PMID 35804950, 2022). "Elevated Notch signaling in breast cancer tumor cells leads to secretion of IL1beta and CCL2 important for recruitment of tumor macrophages." (PMID 35682918, 2022). "CCL2 contributes to the progression of cancer via recruiting MDSCs to form a tumor-supportive immune microenvironment, whereas the inhibition of CCL2 production diminished both the accumulation of MDSC and tumor growth." (PMID 36077785, 2022). "CCL2 possesses both tumor-inhibitory and tumor-promoting effects, depending on the interaction between cancer and host cells." (PMID 35562953, 2022). "In this study, we revealed the roles of tumor cell-derived CCL2 on TAMs polarization and the resistance to trastuzumab in HER2-positive GC." (PMID 35851310, 2022). "The level of CCL2 and IL-17 increased from day 1 after tumor resection and stayed elevated through day 21, indicating sustained post-surgical activation of brain myeloid cells." (PMID 35884700, 2022). "We measured the levels of CCL2 expression in HER2-positive GC tissues, and revealed biological functions of tumor cell-derived CCL2 on tumor-associated macrophages (TAMs) and the trastuzumab resistance." (PMID 35851310, 2022). "CCL2 upregulation and TAM increase are significantly observed in ESCC tumor tissues, and are significantly associated with poor prognosis." (PMID 36211375, 2022). "Colony-stimulating factor-1 (CSF-1) and C−C chemokine ligands, such as CCL2, are crucial tumor-derived factors that mediate the crosstalk between monocytes and tumor cells and foster continuous recruitment and differentiation of monocytes in the TME." (PMID 36679900, 2022). "Simultaneously, treatment of tumor cells with S100A9 significantly increased CCL2 expression, recruited and polarized more macrophages, and formed a CSC–TAM positive feedback loop." (PMID 35740975, 2022). "Previous research has validated that the anti-PD-1 ICIs can prevent the differentiation of osteoclast precursor cells to osteoclasts by intercepting CCL2 generation, which contributes to enhanced anti-tumor immunity." (PMID 36498476, 2022). "They described that the recruitment of myeloid cells such as neutrophils, macrophages, and MDSCs to the tumor microenvironment by tumor cells promotes the secretion of active IL-1β and other proinflammatory mediators such as CCL2, CCL3, and Bv8." (PMID 35681719, 2022).
tumor (continued). "Tumor cell-derived CCL2 decreased M1-like phenotype of TAMs via ZC3H12A-TRAF6/3 signaling, whereas CD40 markedly protected the TRAF6/3 from K63-linked deubiquitination, thereby reactivating the NF-κB signaling." (PMID 35851310, 2022). "An anti-CCL2 antibody was found to inhibit the infiltration of Ly6Chi monocytes and tumor metastasis." (PMID 35707538, 2022). "As one of the critical members of TME cellular components, tumor-associated macrophages (TAMs) perform an indispensable function in the tumor resistance link and can be recruited to the tumor localization by CCL2, CCL5, and CAFs." (PMID 35953863, 2022). "The DEN/CCl4-treated Cxcl10−/− mice, in turn, displayed a significant enhancement of chemokines in tumor tissue in comparison to the surrounding tissue (Ccl5, Ccl2 and Ccl7)." (PMID 35897689, 2022). "Chemokine MCP-5 (CCL12) facilitates tumor metastasis and blockade of CCL2/CCR2 axis enhances CD8+ T cell-mediated antitumor immunity." (PMID 35935577, 2022). "Like in the primary tumor, CCL2 was increased in wounded mice (p < 0.05) and there was a trend for an increase in CCL5 (p = 0.06)." (PMID 36325601, 2022). "In fact, MC38 tumors secreted more myeloid cell-specific chemokines, particularly CCL2 than CT26 cells which led to monocyte recruitment in this tumor." (PMID 35906202, 2022). "Altogether, seven factors were detected both in MC38-conditioned media and MC38 tumor-bearing serum: CCL2, GDF-15, Proliferin, CXCL10, Osteopontin, PCSK9 and Serpin E1." (PMID 35962398, 2022). "Surgical tumor resection can induce immunosuppressive activities by inducing pro-inflammatory and pro-tumorigenic cytokines such as IL-1β, IL-6, IL-10 CCL-2 and TGF-β, which recruit immunosuppressive cells such as MDSCs." (PMID 36611932, 2022). "Research in mouse models and humans has shown that high levels of tumor-derived CCL2 correlate with an increased number of TAMs in the tumor tissue, and also with a poor cancer prognosis." (PMID 35237673, 2022). "The transmission of anti-VEGFA/CCL2/pre-miR-1, anti-miR-31, and pre-miR-206 inhibits tumor growth, tumor angiogenesis, and lung metastasis when administered systemically." (PMID 35909469, 2022). "As an effective chemokine of TAMs, CCL2 indirectly promotes the invasion and metastasis of tumor cells through TAM chemotaxis." (PMID 35320940, 2022). "Monocytes are recruited to the tumor by chemokines such as CCL2, CCL5, CCL7, CCL8, CXCL12, VEGF, and M-CSF, and become TAMs." (PMID 35565420, 2022). "Ccr2 is a chemoreceptor necessary for monocytes/macrophages to migrate towards Ccl2, a chemokine produced by a variety of cells, including tumor cells." (PMID 36376929, 2022). "The antitumor responses of the NF-κB trigger signaling cascade result in T-cell recruitment at the tumor site, leading to tumor regression and activation of chemokines and cytokines possessing the C–C motif and CCL2, respectively." (PMID 36518665, 2022). "CCL2, as an important medium between the tumor and TME, can be secreted by multiple cells in the TME and interacts with immune cells infiltrated in the TME." (PMID 36077785, 2022). "Despite being predominantly an M1-inducing factor, GM-CSF can induce the production of CCL2 from T cells in the tumor microenvironment and the expression of CCR2 on macrophages thus polarizing them to the metastasis-promoting the M2 phenotype." (PMID 35865534, 2022). "Chemoattractants secreted by macrophages that control their recruitment to the tumor site include chemokines, e.g., CCL2 or CCL5, and cytokines, e.g., CSF-1 and members of the VEGF family." (PMID 36077705, 2022). "As a result, ACKR2 expression in the tumor microenvironment decoys CCL2 and impairs the infiltration of NK cells." (PMID 35677043, 2022). "So the CCL2 in TME was produced by both tumor cells and TAMs, with the former one playing a major role." (PMID 36038549, 2022).
tumor (continued). "TNFα produces and maintains a network of other mediators that promote tumor growth and peritoneal spread by stimulating the release of IL-6 and other chemokines such as CCL2 and CXCL12, macrophage migration-inhibitory factor (MIF), and VEGF." (PMID 36142615, 2022). "The regulation of CCL2 by peroxynitrite produced by MDSCs impedes the movement of effector CD8+ T cells toward the tumor site." (PMID 36362050, 2022). "IL-33, Adiponectin, CCL8, GRO, and CCL2 contributed to the juxta-tumor type; the other analytes contributed to the tumor type." (PMID 36539890, 2022). "Metastatic seeding is also suppressed by inhibition of the CCL2–CCR2 pathway and exhaustion of tumor-derived CCL2." (PMID 35911705, 2022). "MCP-1(CCL2) is a chemoattractant cytokine that recruits monocytes from the blood to the tumor site where they then differentiate into macrophages." (PMID 35681702, 2022). "Particularly, considering only MIBC patients, a positive CCL2 expression in tumor cells was associated with poor mean OS, DSS and recurrence-free survival (RFS), while expression of CCL2 in immune cells, was associated with longer OS, DSS, and RFS." (PMID 36699696, 2022). "M-MDSCs are recruited to the TME primarily by tumor-derived CCL2 and CCL5, while PMN-MDSCs are recruited by CCL2 and CCL3." (PMID 35345849, 2022). "For example, blocking CCR2 or CCL2 (CCR2 ligand) expression in tumor cells is particularly effective in alleviating the tumor progression and overcoming the resistance to anti-PD-1 therapy after incomplete radiofrequency ablation." (PMID 35935996, 2022). "The blockade of CCL2 also showed a significant decrease in the number of TAMs recruited into the tumor microenvironment." (PMID 35461243, 2022). "Future investigation is required to explore macrophage mobility in vivo in response to tumor derived Ccl2 and ADMA." (PMID 36376929, 2022). "Collectively, our results demonstrated that Hmga2 knockout in CRC cells inhibited TAM infiltration, M2 polarization, and CCL2 secretion in subcutaneous tumor models." (PMID 34976223, 2022). "In the anti-CCL2 group, there was a smaller fold change in tumor volume with one significant difference observed on Day 6 (p = 0.0089)." (PMID 35461243, 2022). "It has been reported that CCL2 expression is often higher in drug-resistant tumor cell lines than in drug-sensitive tumor cell lines, and silencing or blockade of its expression can re-sensitize cancer cells to anticancer treatment." (PMID 36077785, 2022). "The 5-FU showed a smaller fold change in tumor volume than the control groups and the anti-CCL2 group." (PMID 35461243, 2022). "It has been shown that CCL2 activity inhibition has anti-tumor effects, and that the combination of CCL2 and DTX enhances the therapeutic DTX effect." (PMID 36289628, 2022). "CCL2 chemokine was found to be directly involved in the process of tumour angiogenesis, and its effects are dependent on the ERK1/2 signalling cascade." (PMID 35701366, 2022). "In particular, specific inhibition of CCL2 with antibodies has been shown to reduce tumour growth and dissemination in different experimental models of prostate, breast, lung, liver cancer, or melanoma." (PMID 36439180, 2022). "The tumour immune environment contained high M2 macrophage infiltrate linked with MMP2, MMP14, TGFB1 and CCL2 expression, representing an immune suppressive environment." (PMID 35637530, 2022). "The recruitment of inflammatory monocytes, which express CCR2 (the receptor for chemokine CCL2), as well as the subsequent recruitment of MAMs, is dependent on CCL2 synthesized by both the tumor and the stroma." (PMID 36003772, 2022). "Conversely, other immune cells, such as the M2 type of macrophages, express C-C motif chemokine receptor 2 (CCR2, receptor of CCL2), and which is an irreplaceable factor that promotes tumor metastasis." (PMID 35252165, 2022).
tumor (continued). "In mouse models of breast cancer, the origin of tumor and metastasis associated macrophages can be found in circulating monocytes that are recruited via CCL2 synthesized at least in part by tumor cells." (PMID 35159100, 2022). "Accordingly, abundant tumor infiltration by TAMs as well as elevated circulating levels of TAM-relevant cytokines including CCL2, CCL8 and colony stimulating factor 1 (CSF1) have been linked with poor disease outcome in multiple cohorts of cancer patients." (PMID 36319998, 2022). "Their results indicated that CCL2 silencing inhibited triple negative tumor cell growth and metastasis by decreasing cancer stem cell renewal and M2 macrophage recruitment." (PMID 36403055, 2022). "Polarization of TAMs into the tumor-promoting M2 phenotype is controlled by factors secreted by the tumor and surrounding cells, such as C-C motif chemokine ligand 2 (CCL2)." (PMID 35865534, 2022). "The B16F10 cells produced large amounts of CCL5/RANTES, whereas the ex vivo s.c. tumour also secreted CCL2/MCP-1 and, at much lower levels, CCL3/MIP-1α and CCL4/MIP-1β." (PMID 36241867, 2022). "MiRNA-375 from the apoptotic breast tumor cells improves CCL2 secretion from tumor cells and enhances recruitment of M2-like TAMs." (PMID 35672862, 2022). "miR-200b-3p was enriched in tumor-derived exosomes and transferred to lung, thereby increasing the expression of C-C motif chemokine ligand 2 (CCL2) by targeting PTEN." (PMID 36430471, 2022). "Tumor-derived CCL2 was shown to mediate resistance to radiation by recruiting CCR2+ monocytes in a mouse model of PDAC." (PMID 35404390, 2022). "On the other hand, CCL2 stimulates tumor proliferation, migration, invasion, and angiogenesis and inhibits the autoimmune system." (PMID 36403055, 2022). "The mRNA expression levels of CCL1/5/7/11/17/19/20/22/25 chemokines were found to be elevated in primary tumors compared to normal specimens, while CCL2/3/4/8/13/14/15/16/18/21/23/24/28 were significantly downregulated in tumor samples." (PMID 35725915, 2022). "In co-culture of human PBMCs and tumor cells CD36 regulates macrophage response by enhanced lipid uptake and increased expression of pro-tumor genes in modeled TAMs (Arg1, Ccl2)." (PMID 36686729, 2022). "Our own observations and the increased effectiveness of CCL-2 blockade prompted us to further investigate the role of neutrophils in glioma tumor cell migration." (PMID 35883641, 2022). "In response to proinflammatory responses, such as LPS, TNF-α, or IL-1β, tumor cells produce CCL2 dependent on the activation of the constitutive nuclear factor -κB (NF-κB) pathway." (PMID 35281057, 2022). "This review briefly characterizes CCR4 and its ligands (CCL17, CCL22, and CCL2), and their contributions to immunological and neoplastic diseases." (PMID 36555280, 2022). "An increased plasma concentration of CCL2 was noticed in the tumor tissues of 67NR tumors in the 100 IU group, and in 4T1 tumors from the same group, a tendency to decrease was observed." (PMID 36230508, 2022). "CCL2 expression mediated by snail positive tumor cells undergoing EMT is responsible for tumor progression involving tumor growth and metastasis, and immunosuppression (increase in PD-L1 expression)." (PMID 35692780, 2022). "This fact improves the following activation of the migration and adhesion of genetically modified MSC due to the concentration gradient mediated by SDF-1α, TGF-β1 (transforming growth factor beta), and CCL2 (C-C motif ligand 2) around the tumor." (PMID 35625723, 2022). "Another example about the link between VEGF and CCL2 is that the concurrent use of anti-VEGFA (bevacizumab) and anti-CCL2 therapy inhibits tumor angiogenesis and growth more effectively than treatments alone in CRCs with ETV5 high expression." (PMID 35935996, 2022). "In the same way, breast cancer patients displaying a high CCL2 tumor expression and high resident TAM levels were more prone to present early recurrence." (PMID 36429101, 2022).
tumor (continued). "When CCL2 was blocked by a specific antibody, the recruitment of inflammatory monocytes was impaired, and tumour growth was delayed." (PMID 35365161, 2022). "CCL2 is a well-studied chemokine expressed by tumor cells, macrophages and stromal cells within the TME." (PMID 35715860, 2022). "Overexpression of CCL2 in the tumor microenvironment similarly led to increased TAM infiltration and collagen deposition, which was abrogated by depletion of CD11b+ cells, including macrophages." (PMID 35435599, 2022). "The neutralization of the chemokine CCL2 results in reduced tumor burden in a mouse prostate cancer model." (PMID 36142615, 2022). "Here, we used chemokine neutralization via the CCL2 pathway to target circulating monocytes that differentiate into M2 pro-tumor TAMs." (PMID 35461243, 2022). "In these models of metastasis, once the tumor cells arrive, there is an immediate CCL2-mediated recruitment of CCR2-expressing classical monocytes that promote metastasis seeding and establishment." (PMID 36077870, 2022). "The plasma level of CCL2 was found to be increased in mice bearing HCT116 tumours and treated with PTX + C‐1305." (PMID 35701366, 2022). "As an important and widely studied chemokine in the tumor microenvironment, monocytechemoattractant protein-1 (MCP-1/CCL2) is one of the important members of the CC subfamily of chemokines with two forms, autocrine or paracrine." (PMID 36497150, 2022). "CCL2 is mainly secreted by macrophages and tumor cells, and it can also be secreted by fibroblasts, endothelial cells, and dendritic cells." (PMID 36077785, 2022). "Recent studies have demonstrated that CCL2 plays a pro-tumorigenic function in the tumor microenvironment." (PMID 36403055, 2022). "These tumor-specific DCs are enriched in deep tumor tissue, correlate with worse clinical outcomes of patients, and are thought to be activated by CCL2 within the TME to promote cancer progression." (PMID 35757757, 2022). "This possibility is highly supported by the fact that joint inhibition of CXCR1/2, CCR2 and CCR5 led to complete inhibition of tumor cell invasion and of CCL2 and CCL5 production." (PMID 35205789, 2022). "Monocyte chemoattractant protein-1 (MCP-1) is a member of the CC-motif chemokine family (as CCL2); MCP-1, a chemokine, is also one of the key agonists in the recruitment of macrophages to tumor sites." (PMID 36131942, 2022). "Macrophages can be induced to M2-TAM by tumor cell–derived C-C motif chemokine ligand 2 (CCL-2), transforming growth factor beta (TGF-β), and intercellular adhesion molecule 1 (ICAM-1) and then enhance the malignant phenotype of tumor cells." (PMID 35739593, 2022). "Osteoblasts, in turn, secrete RANKL and CCL2 to promote osteoclastogenesis and bone deterioration, favoring the growth of metastatic PCa tumor cells in the bone microenvironment." (PMID 35058441, 2022). "We showed that MAMs differentiate from circulating classical Ly6C+ CCR2+ monocytes (CMs) that are recruited to the metastases by tumor-cell-derived CCL2." (PMID 36077870, 2022). "Many studies indicate that CCL2 facilitates tumor cell metastasis by promoting epithelial-to-mesenchymal transformation and the recruitment of macrophages." (PMID 36077785, 2022). "CXCL10 and CCL2 were also found in the tumor and TME, where they co-localized with Nestin+, Iba-1+, CD163+, or CD16+ cells, suggesting that they had a similar distribution and location." (PMID 35269652, 2022). "The anti-tumor effects of blocking the CCL2/CCR2 and CXCLs/CXCR2 axes by CCR2 and CXCR2 antagonists in combination with TACE were evaluated in HCC rats." (PMID 36403057, 2022). "In hepatocellular carcinoma, CnP inhibits the expression of α-SMA, the activation marker of CAFs, and the tumor-promoting cytokine production such as IL-6, IL-8, and CCL-2 of CAFs." (PMID 35327514, 2022).